CCL13 (C-C motif chemokine ligand 13)
Description:
Chemotactic factor that attracts monocytes, lymphocytes, basophils and eosinophils, but not neutrophils. Signals through CCR2B and CCR3 receptors. Plays a role in the accumulation of leukocytes at both sides of allergic and non-allergic inflammation. May be involved in the recruitment of monocytes into the arterial wall during the disease process of atherosclerosis. May play a role in the monocyte attraction in tissues chronically exposed to exogenous pathogens.
Synonyms: MCP-4; NCC1; SCYA13; NCC-1; SCYL1; CKb10; MGC17134
Tractability: Antibody: its Gene Ontology location is reachable by antibodies, with high confidence; UniProt places it where antibodies can reach, with medium confidence; UniProt predicts a signal peptide or a membrane-spanning region.
Gene: Protein-coding gene on chromosome 17 (34,356,480 to 34,358,610, forward strand). Ensembl gene ENSG00000181374.
Subcellular location: Secreted
Pathways (Reactome):
Signal Transduction: Chemokine receptors bind chemokines; G alpha (i) signalling events
Gene Ontology:
Molecular function: chemokine activity; protein binding; CCR chemokine receptor binding; signaling receptor binding
Biological process: antimicrobial humoral immune response mediated by antimicrobial peptide; cytoskeleton organization; eosinophil chemotaxis; killing of cells of another organism; regulation of cell shape; cell-cell signaling; chemokine-mediated signaling pathway; chemotaxis; inflammatory response; intracellular calcium ion homeostasis; positive regulation of cell migration; signal transduction; immune response
Cellular component: extracellular region
Genetic constraint (gnomAD): Loss-of-function variants: 2 observed, 2.03 expected, observed/expected ratio (o/e) 0.98, 90% interval 0.36 to 1.87. That is too few expected variants to judge how well the gene tolerates losing a copy. Missense variants: 70 observed, 71.13 expected, observed/expected ratio (o/e) 0.98, 90% interval 0.81 to 1.2. Synonymous variants: 22 observed, 27 expected, observed/expected ratio (o/e) 0.81, 90% interval 0.58 to 1.16.
Homologues: Orthologues: chimpanzee CCL13 (99% identical), macaque CCL13 (94% identical), dog CCL13 (67% identical), zebrafish cxcl32b.1 (33% identical). Paralogues in human: CCL2 (65% identical), CCL11 (64% identical), CCL7 (63% identical), CCL8 (62% identical), CCL3L3 (38% identical), CCL16 (37% identical), CCL4 (37% identical), CCL24 (36% identical), CCL26 (36% identical), CCL3 (35% identical), CCL4L2 (35% identical), CX3CL1 (34% identical), and 14 more.
Diseases named in the same sentence as CCL13 in open-access papers:
CCL13 is named in the same sentence as 133 diseases in open-access papers, as found by Europe PMC text mining. Sharing a sentence is not in itself a finding about the gene and the disease. The quoted sentences say what the papers report.
asthma (21 papers, 2008 to 2025). "CCL13 is implicated in asthma, rheumatic diseases, skin conditions (atopic dermatitis and alopecia areata), and cancer." (PMID 38601164, 2024). "CCL13 (MCP-4) has been implicated in inflammatory processes in asthma, and CCL17 (TARC) is a biomarker of atopic dermatitis severity with a reported case of transient increase after FIA." (PMID 35202004, 2022). "In children with viral exacerbation of asthma, CCL13 is upregulated during symptomatic disease and has been associated with macrophage recruitment." (PMID 41354730, 2025). "TLR7 agonists can increase the expression of interferon and C-C motif chemokine ligand 13 (CCL13) in nasal mucosa of patients with asthma and allergic rhinitis." (PMID 38341589, 2024). "Elevated blood CCL13 concentrations have been observed in children with severe asthma, and it has been suggested that blood CCL13 levels can help in characterizing the severity of asthma in children." (PMID 37153575, 2023). "CCL13 and other chemokines within its family have been extensively investigated in diseases such as asthma, COPD, allergic pneumonia, and upper and lower respiratory tract infections." (PMID 37153575, 2023). "When compared to patients with asthma who had their condition under control with glucocorticoids, people with uncontrolled asthma had greater CCL13 levels." (PMID 37153575, 2023). "The role of the CCL13-Th2 axis in promoting the entry of M2 macrophages and eosinophils into the airways and triggering airway inflammation in asthma is well established." (PMID 37153575, 2023). "The levels of interferon‐γ (IFN‐γ), tumor necrosis factor‐a (TNF‐α), chemokine CCL22 (CCL22), interleukin 12 (IL‐12), chemokine CCL4 (CCL4), chemokine CCL2 (CCL2), and chemokine CCL13 (CCL13)were significantly higher in the acute asthma group than in the stable asthma group." (PMID 39508721, 2024). "In addition, similar to asthma, increased responsiveness of CCL13 to TLR7/8 agonists has also been observed in allergic rhinitis." (PMID 37153575, 2023). "Airway epithelial cells can be activated by cytokines (IL-1β, IFN-γ,TNF-α, etc.)or PAMPS (Pathogen-related molecular patterns) via the TLRs-NF-κb pathway and releases CCL13, which recruits eosinophils and promotes the polarization of M2 macrophages to mediate the progression of asthma." (PMID 37153575, 2023). "Monocytes and eosinophils in sputum from children with asthma exhibited CCL13 and CCR3, but lymphocytes solely expressed CCL13; CCL13 is negatively correlated with peak expiratory flow and is downregulated in asthma remission." (PMID 37153575, 2023). "Furthermore, Toll-like receptor 7 and 8 (TLR7/8) mediates the antiviral immune response by recognizing mainly viral RNA, and the increased response of the CCL13 gene to TLR7/8 agonists in the nasal mucosa of asthma patients may reflect the role of the virus in asthma progression." (PMID 37153575, 2023). "CCR3 is one of the most relevant chemokine receptors in asthma, and its ligands are CCL3, CCL5, CCL11, and CCL13." (PMID 35743888, 2022). "We chose to focus our functional studies on four cytokines that were differentially expressed between fatal asthma- and non-asthma-derived ASM and were also modified by vitamin D treatment in fatal asthma-derived ASM (i.e., CCL2, CCL13, CXCL12, IL8)." (PMID 26207385, 2015). "Our RNA-Seq results showing that CCL2, CCL13, and IL8 mRNA levels were elevated in fatal asthma-derived ASM are consistent with these previous studies showing elevated levels in ASM (for CCL2) and other tissues." (PMID 26207385, 2015). "Follow-up qPCR and individual analyte ELISA experiments were conducted for four cytokines (i.e. CCL2, CCL13, CXCL12, IL8) to measure TNFα-induced changes by asthma status and vitamin D treatment." (PMID 26207385, 2015). "The CCL2, CCL13, CXCL12, and IL8 cytokine genes selected for experimental follow-up are known to be involved in asthma related processes." (PMID 26207385, 2015).
asthma (continued). "CCL13 is a potent chemokine which attracts CCR3+ cells like eosinophils, Th2-lymphocytes, basophils and correlates with asthma exacerbation." (PMID 24612750, 2014). "This study provides evidence for an augmented expression of CCL13, CCL17, and CLEC10A in AMΦ from patients with mild asthma during episodes of acute allergic airway inflammation." (PMID 24612750, 2014). "The chemokine MCP-4/CCL13 attracts granulocytes, monocytes, and T cells, and it has been proposed as a biomarker in asthma being up-regulated during both Th1- and Th2-type hyper-responses." (PMID 23855879, 2013). "We found that the following chemokines were significantly up-regulated in the serum in asthma compared to healthy subjects CCL2, CCL4, CCL11 and CCL13 (p < 0.05)." (PMID 19602238, 2009). "The serum levels of TNF‐α (p = 0.025), IFN‐γ (p = 0.011), CCL22 (p = 0.022), IL‐12p70 (p = 0.021), CXCL10 (p = 0.028), CCL2 (p = 0.028), CCL13 (p = 0.024), IL‐4 (p = 0.026), IL‐13 (p = 0.024), and CCL11 (p = 0.028) were found to be downregulated in stable asthma when compared to acute asthma." (PMID 39508721, 2024). "Studies on CCL3, CCL7, CCL8, CCL13, and CXCL12 in relation with asthma are limited." (PMID 28848734, 2017). "Fatal asthma-derived ASM secreted greater TNFα-induced IL8 and lower TNFα-induced CXCL12 as compared to non-asthma-derived ASM, while TNFα-induced CCL2, and CCL13 levels between fatal asthma- and non-asthma-derived ASM were not significantly different." (PMID 26207385, 2015). "The mRNA differences of CCL13 between fatal asthma- and non-asthma-derived ASM did not extend to protein secretion levels." (PMID 26207385, 2015). "We found that TNFα treatment induced CCL2, CCL13, and IL8 mRNA expression in most fatal asthma- and non-asthma-derived ASM samples, but TNFα treatment did not induce CXCL12." (PMID 26207385, 2015). "At last, bronchoalveolar lavage and biopsy samples’ content of CCL13 and other MCP family members may not be specific in identifying asthma, tuberculosis, nodular disease, and chronic bronchitis." (PMID 37153575, 2023). "Thus, consistency between mRNA and protein secretion levels is high for TNFα-induced changes, and present to varying degrees among the four cytokines for changes between fatal asthma- and non-asthma-derived ASM, with CXCL12 and IL8 showing the greatest consistency and CCL13 the weakest." (PMID 26207385, 2015).
COVID-19 (19 papers, 2020 to 2025). A disease caused by infection with severe acute respiratory syndrome coronavirus 2. "Furthermore, genes encoding CCL7, CCL8, and CCL13 were also found in bronchoalveolar lavage (BAL) in patients with COVID-19." (PMID 36851766, 2023). "A similar decrease in COVID-19 patients was observed for CCL13/MCP-4 (89.1 ± 9.0 vs. 155.9 ± 21.5 pg/mL, p = 0.01) and CCL22/MDC (523.9 ± 55.0 vs. 914.9 ± 109.4 pg/mL, p = 0.007)." (PMID 36851770, 2023). "We observed increased expression of CCL13, CCL3, CXCL11 and CXCL10 which were associated with severe COVID-19 outcome in humans." (PMID 36298826, 2022). "In fact, when compared to controls, amniotic fluid from COVID-19-affected pregnancies demonstrated elevated levels of several pro-inflammatory cytokines, including IL-12 p40, CCL4, CCL7, CCL13, TNF, IL-1a, IL-17A, and IL-17E." (PMID 39390219, 2024). "Of the 16 mediators elevated in early COVID-19 compared with healthy controls, 11 decreased over time (CCL3, CCL4, TNF-α, IL-6, CCL13, IL-4, IFN-α2a, CXCL10, CXCL11, IL-2, and IL-12)." (PMID 35397798, 2022). "While some genes involved in monocyte and lymphocyte migration and function were expressed in the COVID-19(+) TV group (CCL13, CCL8, and CCL20), a greater number of these genes were expressed in the COVID-19(-) PU control group (CCL19, CCL18, CXCL13, CCL4, CCL5, CXCL9)." (PMID 37026002, 2023).
psoriasis (7 papers, 2017 to 2025). An autoimmune condition characterized by red, well-delineated plaques with silvery scales that are usually on the extensor surfaces and scalp. "Fibroblasts produced a number of chemokines (CCL13, CCL19, CCL2, CCL8, CXCL1, CXCL12, CXCL2, CXCL3) that linked to receptors expressed by myeloid cells and T cells, suggesting an important role for fibroblasts in recruiting immune cells in psoriasis." (PMID 37308489, 2023). "Although several chemokines, such as CCL13, CXCL12, CXCL10, CCL27, and CCR6, have been identified in the context of psoriasis, CXCL10, in particular, has been suggested as a biomarker for psoriasis progression." (PMID 38829444, 2024).
atherosclerosis (6 papers, 2013 to 2023). A disease characterized by the build-up of fatty material and calcium deposition in the arterial wall resulting in partial or complete occlusion of the arterial lumen. "Furthermore, in older AD patients, CCL13 is considered a risk factor for atherosclerosis, indicating that these people might gain from screening for and treatment of cardiovascular disease." (PMID 37153575, 2023). "Earlier on, a study of adipokines in obesity and related comorbidities suggests that CCL13, a brand-new biomarker for extreme obesity, may exacerbate subclinical atherosclerosis in persons with obesity by affecting circulating levels of major atherosclerotic markers." (PMID 37153575, 2023).
atopic dermatitis (6 papers, 2014 to 2024). "Atopic dermatitis (AD) and alopecia areata are the two primary dermatological disorders linked to CCL13 that have been described in the literature, with the former being more clearly linked." (PMID 37153575, 2023). "A number of chemokines [CCL2, CCL3, CLL4, CCL8, CCL13, CCL19, chemokine (C-X-C motif) ligand (CXCL) 1, CXCL6, CXCL16] were upregulated in sensitized dogs after allergen challenge, similar to what is observed in human atopic dermatitis." (PMID 25098772, 2014).
depression (6 papers, 2020 to 2024). "CCL13 was also negatively associated with GDS scores (r = −0.283, p = 0.018), reflecting the severity of depression." (PMID 35069588, 2021). "We also found that the level of CCL13 was negatively associated with GDS scores, reflecting the severity of depression." (PMID 35069588, 2021). "High levels of CCL2 and CCL13 were observed in patients with depression compared to healthy control, evoking the possibility that immune cell mobilization may be involved in the disease." (PMID 38473935, 2024).
rheumatoid arthritis (6 papers, 2010 to 2025). A chronic, systemic autoimmune disorder characterized by inflammation in the synovial membranes and articular surfaces. "The functions of MCP-4/CCL13 include secretion of proinflammatory cytokines; increased serum levels of MCP-4/CCL13 were found in patients with knee osteoarthritis (OA) and rheumatoid arthritis (RA)." (PMID 38304854, 2024). "CCL13 was discovered in the synovial fluid of patients with rheumatoid arthritis (RA) and stimulates the migration of monocytes." (PMID 20181226, 2010). "In rheumatoid arthritis, estrogen has been found to decrease synovial fibroblast death and increase CCL13 expression, and this process may explain why women are more likely than males to get RA." (PMID 37153575, 2023).
breast carcinoma (5 papers, 2019 to 2023). "Moreover, CCL13 is linked to 2-microglobulin (2-MG) levels in multiple myeloma, poor prognosis in prostate adenocarcinoma, and cell proliferation in breast cancer." (PMID 37153575, 2023). "Chronic hypoxia does not seem to affect the expression of CCL13, according to in vitro experiments using breast cancer, hepatocellular carcinoma, and lung adenocarcinoma cells." (PMID 37153575, 2023). "Chronic hypoxia does not change the expression of CCL13/MCP-4, as confirmed by research on breast cancer cells, hepatocellular carcinoma cells, and lung adenocarcinoma cells." (PMID 32781743, 2020).
nasal polyp (5 papers, 2015 to 2023). "One study showed that fibroblasts may be a major source of Th2 chemokines and that TLR2, 3, 4, and 5 ligands can synergistically induce the production of CCL13 in nasal polyp fibroblasts when combined with IL-4, while TLR7/8 or 9 ligands do not induce its production." (PMID 37153575, 2023). "The function of CCL13 in rheumatic diseases, skin conditions, and cancer is comparatively well-established, and some studies also suggest that it may be involved in ocular disorders, orthopedic conditions, nasal polyps, and obesity." (PMID 37153575, 2023). "Expression levels of ALOX5AP, AQP9, CCL13, EMR3, F13A1, GAPT, and NCF2 were significantly higher in nasal polyp samples from ACRSwNP patients compared with the expression levels in samples from healthy subjects." (PMID 36059464, 2022). "hsa-mir-27a-3p may promote the occurrence of inflammation and the formation of nasal polyps by regulating the expression of AZGP1, NCF2, CCL13, MUC7, PIP, and STATH." (PMID 36059464, 2022).
Obesity (5 papers, 2016 to 2024). Accumulation of substantial excess body fat. "All these discoveries implies that CCL13 and hs-CRP may be markers of chronic inflammation in obesity and periodontal disease." (PMID 37153575, 2023).
Allergy (4 papers, 2016 to 2023). An allergy is an immune response or reaction to substances that are usually not harmful. "Eosinophil attractants, CCL11 and CCL13 chemokines, are involved in allergy responses." (PMID 37598287, 2023). "In addition, we observed evidence of intercellular communication via genes implicated in type 2 immunity (CCL11, CCL13, CD5L, IL4, IL5, IL13, IL24) and allergy-linked inflammation (CCL19)." (PMID 35483355, 2022). "Although CCR1 and CCR3 are receptors for CCL13-induced eosinophil-triggered allergies, it is crucial to remember that CCR1 also has a function in CCL13-induced allergic pneumonia." (PMID 37153575, 2023).
atherosclerotic heart disease (3 papers, 2010 to 2021). "Among these, it is noteworthy mentioning CCL13, a chemotactic factor able to identify with a very high degree of accuracy subjects with clinically significant atherosclerotic heart disease." (PMID 33572602, 2021).
lung carcinoma (3 papers, 2021 to 2024). "We found that TREM2 was strongly associated with CCL2, CCL3, CCL13, and CCL17 in lung cancer." (PMID 39135069, 2024). "RT-qPCR analyses of CCL2, CCL3, CCL13, and CCL17 revealed that the transcription level of CCL2 in lung cancer was notably elevated compared to that in healthy lung." (PMID 39135069, 2024).
ovarian carcinoma (3 papers, 2022 to 2024). A malignant neoplasm originating from the surface ovarian epithelium. "Next, we explored whether CCR2 was involved in the enhanced effect of CCL13 on ovarian cancer cell growth in vitro." (PMID 38680032, 2024). "Furthermore, we verified that CCR2 was the receptor of CCL13 when ovarian cancer with oestrogen treatment." (PMID 38680032, 2024). "In addition, we confirmed that oestrogen‐induced exosomal CCL13 could promote CCL13 release to regulate ovarian cancer cell proliferation, migration, invasion and EMT." (PMID 38680032, 2024). "The activated M2 macrophage released CCL13, binding to CCR2 and thus promoted ovarian cancer tumour growth and metastasis in vitro and in vivo." (PMID 38680032, 2024). "CCL13 is a M2 macrophage-secreted chemokine, an important chemoattractant for monocytes and T-cells, and has been correlated with poor prognosis and tumor progression in ovarian cancer and oral squamous carcinoma, with no information on its involvement in PDAC." (PMID 38167013, 2024).
periodontitis (3 papers, 2021 to 2023). An acute or chronic inflammatory process that affects the tissues that surround and support the teeth. "The CCL13 (also called Monocyte Chemoattractant Protein 4- MCP4) is involved in the inflammatory process of several diseases and its levels are increased in the gingival crevicular fluid (GCF) of patients with periodontitis whereas CXCL11 is related with Th1 cell accumulation in inflamed mucosa." (PMID 35048045, 2021).
viral infection (3 papers, 2023 to 2025). "Together, these analyses suggest a CCL13-CD1c+ DC-centered program at baseline that couples chemokine to T cell readiness, potentially explaining protection against primary viral infection." (PMID 41354730, 2025).
allergic rhinitis (2 papers, 2023 to 2024). Inflammation of the nasal mucous membranes caused by an IgE-mediated response to external allergens. "In patients with seasonal allergic rhinitis, under nasal allergen stimulation, the level of CCL13 in nasal secretions increases 3.7-fold, while IL-10 and IL-4 significantly decrease; CCL13 may worsen, while IL-10 may alleviate nasal mucosa allergy." (PMID 37153575, 2023).
Alzheimer disease (2 papers, 2024 to 2026). A progressive, neurodegenerative disease characterized by loss of function and death of nerve cells in several areas of the brain leading to loss of cognitive function such as memory and language. "CCL13, an inflammation‐linked chemokine, has been observed to be elevated in the plasma of individuals suffering from aging‐related cognitive impairment, and it demonstrates moderate diagnostic efficacy in Alzheimer's disease (ad)." (PMID 41545024, 2026).